NFYA (nuclear transcription factor Y subunit alpha)
Description:
Component of the sequence-specific heterotrimeric transcription factor (NF-Y) which specifically recognizes a 5'-CCAAT-3' box motif found in the promoters of its target genes. NF-Y can function as both an activator and a repressor, depending on its interacting cofactors. NF-YA positively regulates the transcription of the core clock component BMAL1.
Synonyms: NF-YA; HAP2; CBF-B; CBF-A
Tractability: PROTAC: ubiquitination databases record sites on it; its protein half-life has been measured.
Gene: Protein-coding gene on chromosome 6 (41,072,946 to 41,102,403, forward strand). Ensembl gene ENSG00000001167.
Subcellular location: Nucleus
Subcellular location (Human Protein Atlas): Nucleoplasm
Pathways (Reactome):
Cellular responses to stimuli: ATF4 activates genes in response to endoplasmic reticulum stress; ATF6 (ATF6-alpha) activates chaperone genes
Metabolism: Activation of gene expression by SREBF (SREBP); PPARA activates gene expression
Gene expression (Transcription): FOXO-mediated transcription of cell death genes
Gene Ontology:
Molecular function: DNA binding; DNA-binding transcription activator activity, RNA polymerase II-specific; protein binding; RNA polymerase II cis-regulatory region sequence-specific DNA binding; transcription cis-regulatory region binding; DNA-binding transcription factor activity; DNA-binding transcription factor activity, RNA polymerase II-specific; sequence-specific DNA binding
Biological process: positive regulation of transcription by RNA polymerase II; regulation of DNA-templated transcription; regulation of transcription by RNA polymerase II; positive regulation of DNA-templated transcription; transcription by RNA polymerase II
Cellular component: CCAAT-binding factor complex; nucleoplasm; nucleus; protein-DNA complex; RNA polymerase II transcription regulator complex; chromatin
Genetic constraint (gnomAD): Loss-of-function variants: 23 observed, 47.89 expected, observed/expected ratio (o/e) 0.48, 90% interval 0.34 to 0.68. The upper end of that interval is the gene's LOEUF score, 0.68, which puts it in group 2 of 6, group 1 being the genes least tolerant of losing a copy. Missense variants: 213 observed, 428.29 expected, observed/expected ratio (o/e) 0.5, 90% interval 0.44 to 0.56. Synonymous variants: 142 observed, 152.61 expected, observed/expected ratio (o/e) 0.93, 90% interval 0.81 to 1.07.
Homologues: Orthologues: chimpanzee NFYA (100% identical), dog NFYA (100% identical), macaque NFYA (100% identical), rabbit NFYA (100% identical), rat Nfya (100% identical), mouse Nfya (99% identical), guinea pig NFYA (99% identical), pig NFYA (98% identical), tropical clawed frog nfya (86% identical), zebrafish nfya (74% identical), zebrafish nfyal (72% identical), Drosophila melanogaster Nf-YA (33% identical), and 2 more.
Diseases named in the same sentence as NFYA in open-access papers:
NFYA is named in the same sentence as 59 diseases in open-access papers, as found by Europe PMC text mining. Sharing a sentence is not in itself a finding about the gene and the disease. The quoted sentences say what the papers report.
breast carcinoma (13 papers, 2016 to 2026). "Our analysis of NFYA splicing variant expression in breast cancer subtypes indicated a strong correlation between the expression pattern of NFYA splicing variants and breast cancer subtypes." (PMID 37268670, 2023). "In this study, we found that blockade of the lipogenesis pathway by NFYA deficiency suppresses the malignant behavior of Claudinlow breast cancer cells." (PMID 37268670, 2023). "In the present study, we also found that compared with non-transformed mouse mammary epithelial cells (NMuMG cells), breast cancer cells isolated from mouse breast tumour tissue showed significantly increased expression of both NFYA variants." (PMID 37268670, 2023). "Interestingly, alternatively spliced isoforms of MYO18 A and NFYA have been linked to prognosis in breast cancer patients, while FN1 is a critical component of the extracellular matrix that has been implicated in tumor progression and metastasis." (PMID 40316533, 2025). "Given the increased expression of NFYA in breast cancer cells, we first generated NFYA-deficient TNBC cells using the CRISPR/Cas9 system in SUM159 cells and examined whether NFYA contributes to the malignant behavior of TNBC." (PMID 37268670, 2023). "Although these results suggest that NFYA plays an essential role in the malignant behavior of breast cancer, the functional differences between NFYA variants remain unclear because of the absence of functional domains in the spliced exon." (PMID 37268670, 2023). "We then used normal human mammary epithelial cells (HMLE cells) and epithelial breast cancer cells (MDA-MB-468 cells) to confirm that conversion of the NFYA splicing variant expression is not only dependent on EMT status between cell lines, but also occurs with intracellular EMT progression." (PMID 37268670, 2023). "NFYA has two types of splicing variants: a long-form (NFYAv1) and a short-form (NFYAv2) that lacks the 29 amino acids encoded by exon 3, including the Q-rich transactivation domain, and these two variants have been reported to perform different functions in breast cancer." (PMID 36092708, 2022). "We found that exon 40 in the MYO18A gene and exon 3 in the NFYA gene were not only downregulated in Snord67 knockout cells, but also positively correlated with Snord67 expression levels in breast cancer patients." (PMID 40316533, 2025). "In contrast, the FASN inhibitor cerulenin reduced CPT1A expression only in NFYA wild-type cells, suggesting that NFYA regulates breast cancer malignant behavior by controlling de novo lipogenesis by regulating ACACA and FASN expression." (PMID 37268670, 2023). "Evaluation of mean intensity of NFYA revealed that the highest expression among the breast cancer cell lines was observed in MDA-MB 231 [, 7.26 ± 0.15)] which was statistically different compared to normal donors’ PBMCs (5.9 ± 0.52, p = 0.016)." (PMID 31370904, 2019). "Among these lncRNA LINC01016 regulates ERα, associated with survival and prognosis of breast cancer, LINC00578 showed association with lung cancer and pancreatic cancer, and LINC01016-miR-302a-3p/miR-3130-3p/NFYA/SATB1 axis was found to regulate endometrial cancer." (PMID 36072894, 2022). "While some of the top candidates have been previously reported to play a role in cancer (FLNB, MAP3K7, NFYA, and ESYT2) others were identified to be breast cancer-relevant for the first time (NEDD4L, MARK2, ABI1)." (PMID 38664594, 2024). "In addition, functional differences among NFYA splicing variants might not be limited to TNBC but also general in breast cancers because NFYA deficiency does not affect the cell growth and sphere formation in HMLE and MCF7 cells predominantly expressing NFYAv2." (PMID 37268670, 2023).
lung carcinoma (12 papers, 2015 to 2023). "NFYA also inhibits the tumor suppressor function in lung cancer through recruiting the transcriptional repressor to the promoter of a tumor suppressor." (PMID 35051313, 2022). "A study showed that the cell viabilities of lung cancer cell lines could be significantly abrogated by the overexpression of PANDAR, which was shown to detain and disable the Bcl-2 transcription factor Nuclear Transcription Factor Y Subunit Alpha (NF-YA)." (PMID 34692550, 2021).
endometrial cancer (8 papers, 2017 to 2024). Primary or metastatic malignant neoplasm involving the endometrium (mucous membrane that lines the endometrial cavity). "LINC01016‐miR‐302a‐3p/miR‐3130‐3p/NFYA/SATB1 axis plays a crucial role in the occurrence of endometrial cancer." (PMID 33216456, 2021). "This study was the first to show that the LINC01016–miR-302a-3p/miR-3130-3p/NFYA/SATB1 axis played a crucial role in the occurrence of endometrial cancer." (PMID 29467441, 2018). "In our study, NFYA expression was elevated in endometrial cancer tissues and inhibition of NFYA hindered cancer cell progression." (PMID 29467441, 2018). "LINC01016 and miR-302a-3p/miR-3130-3p made up two bidirectional regulatory feedback loops that mediated the malignant phenotype of endometrial cancer cells via NFYA and its target SATB1." (PMID 29467441, 2018). "We concluded that NFYA played a positive role in regulation of the malignant phenotype of endometrial cancer cells via the LINC01016-miR-302a-3p/miR-3130-3p axis." (PMID 29467441, 2018). "With a high expression level in endometrial cancer tissues, NFYA directly targeted the promotor region of SATB1 and contributed to the transcription of SATB1." (PMID 29467441, 2018). "Collectively, these results suggested that NFYA contributed to the malignant behavior of endometrial cancer cells by directly binding to the promotor region of SATB1." (PMID 29467441, 2018). "NFYA could promote self-renewal of hematopoietic stem cell and inhibition of NFYA expression could hinder the progression of endometrial cancer." (PMID 31537905, 2020). "Nevertheless, the role of NFYA in endometrial cancer is still ambiguous." (PMID 29467441, 2018). "Hence, SATB1 was identified as a downstream gene target in LINC01016-miR-302a-3p/miR-3130-3p-NFYA regulatory axis in endometrial cancer." (PMID 29467441, 2018). "Overexpression of NFYA increased the proportion of endometrial cancer cells in G2–M phase." (PMID 29467441, 2018). "Collectively, our results illustrated that LINC01016-miR-302a-3p/miR-3130-3p-dependent regulation modulated the expression of NFYA and SATB1 in endometrial cancer cells." (PMID 29467441, 2018). "Here, we found that LINC01016 promoted oncogenic processes by targeting miR-302a-3p and miR-3130-3p and inducing the overexpression of NFYA, thus affecting SATB1 expression in endometrial cancer cells." (PMID 29467441, 2018). "The expression levels of LINC01016, miR-302a-3p, miR-3130-3p, NFYA, and SATB1 were evaluated by quantitative real-time polymerase chain reaction (qRT-PCR) in 33 endometrial cancer tissues and 20 normal tissues." (PMID 29467441, 2018). "Given that NFYA and SATB1 were found to be overexpressed in endometrial cancer tissues, we explored the role of NFYA in malignant progression in endometrial carcinogenesis." (PMID 29467441, 2018). "We confirmed that NFYA and SATB1 mRNA and protein were overexpressed in endometrial cancer tissues compared to normal tissues by qRT-PCR and western blotting and immunohistochemistry (IHC)." (PMID 29467441, 2018). "Mir-3130 has been found to inhibit the expression of NDUFS1 to promote the invasiveness of lung adenocarcinoma in vivo and in vitro and could also regulate the miR-3130-3p/NFYA/SATB1 axis to promote the occurrence and development of endometrial cancer cells." (PMID 39591000, 2024). "The LINC01016/miR-302a-3p/miR-3130-3p/NFYA/SATB1 axis highlighted a novel class of lncRNA–miRNA interactions, which may guide future treatments in endometrial cancer." (PMID 29467441, 2018).
colorectal cancer (6 papers, 2010 to 2025). A primary or metastatic malignant neoplasm that affects the colon or rectum. "For example, HNF4A, which controls epithelial cell differentiation and homeostasis, was overrepresented in yMB, whereas NFYA, which was underrepresented in yMB, has been linked to gastric adenocarcinomas and aggressiveness of colorectal cancer." (PMID 40176137, 2025). "Among the top ten more active transcription factors in left-sided colorectal cancer we found a significant enrichment of transcription factors associated with unfolded protein response (NFYA and CEBPG, hypergeometric test, FDR < 0.01)." (PMID 38438786, 2024).
gastric cancer (6 papers, 2021 to 2023). A primary or metastatic malignant neoplasm involving the stomach. "Increasing evidence has shown that NFYA plays a key role in various cancers, including lung, breast, and gastric cancer." (PMID 35568893, 2022). "Similarly, the expression of NYFA and sex determinant region Y are independent prognostic markers in gastric cancer, and that NFYA promotes growth of clear cell renal cell carcinoma (ccRCC) through the regulation of cyclins activity." (PMID 37189841, 2023).
prostate carcinoma (6 papers, 2021 to 2025). A carcinoma that arises from epithelial cells of the prostate gland. "Prostate cancer samples in GSE179990, with high expression for NFYA (both its long and short isoforms), showed similar pathways to be present within highly upregulated genes (respectively)." (PMID 39857756, 2025). "From the PCA analysis results, we found that the roles of FOXA1, NFYA, and FOXP1 in regulating stemness genes in normal prostate samples were changed by comparing those in prostate cancer samples." (PMID 33985534, 2021).
cervical carcinoma (5 papers, 2019 to 2024). A carcinoma arising from either the exocervical squamous epithelium or the endocervical glandular epithelium. "NFYA promoted cell proliferation and tumorigenic properties by transcriptional activation of SOX2 in cervical cancer." (PMID 35409328, 2022).
hepatocellular carcinoma (5 papers, 2017 to 2023). A malignant tumor that arises from hepatocytes. "Finally, we examined the correlation between NFYA and PCK1 in human hepatocellular carcinomas." (PMID 36092708, 2022). "Taking into account the fact that NFYA is the most important overall activator in the network, we can argue that under a repression of NFYA via ZHX2, the consequence will be a general inhibition of the transcriptional program, which may result for instance, in the progression of liver carcinoma." (PMID 29119102, 2017).
liver cancer (4 papers, 2017 to 2023). An epithelial or non-epithelial malignant neoplasm that arises from the liver. "We also found in Kaplan–Meier survival curves that a high expression of either PNPase, SP1 or NFY subunit A (NFYA) is associated with a poor prognosis in liver cancer." (PMID 36232701, 2022). "Therefore, to investigate the correlation between each NFYA variant and PCK1 in 297 liver cancers using RNA-seq data from TCGA, we classified by the logFC of VIM/CDH1 into two groups: those predominantly expressing NFYAv1 (1 < logFC) and those predominantly expressing NFYAv2 (logFC < −1)." (PMID 36092708, 2022).
head and neck squamous cell carcinoma (3 papers, 2021 to 2025). A squamous cell carcinoma that arises from any of the following anatomic sites: lip and oral cavity, nasal cavity, paranasal sinuses, pharynx, larynx, and salivary glands.
osteosarcoma (3 papers, 2016 to 2020). A usually aggressive malignant bone-forming mesenchymal neoplasm, predominantly affecting adolescents and young adults. "In osteosarcoma cells, NFYA has been shown to stimulate transcription of bone sialoprotein, a major protein in the extracellular matrix of bone." (PMID 27056980, 2016).
breast tumor (2 papers, 2023 to 2025). "That is, in patients whose LN metastasis displayed increased Snord67 expression relative to the primary breast tumor, the inclusion of MYO18A exon 40 and NFYA exon 3 was also increased in the LN tumor relative to the primary breast tumor." (PMID 40316533, 2025). "Moreover, the change in PSI for these two alternative exons significantly correlated with the change in Snord67 expression in matched pairs of primary breast tumors and LN metastases (MYO18A exon 40: Pearson r = 0.54, p = 0.0066; NFYA exon 3: Pearson r = 0.51, p = 0.011)." (PMID 40316533, 2025).
clear cell renal cell carcinoma (2 papers, 2022 to 2023). "In clear cell renal cell carcinoma, transcription factor NFYA was reported to be able to simultaneous transactivating CCND1 and CDK4 to promote G1/S cycle transition thus accelerating tumor development and predicting poor prognosis." (PMID 35365622, 2022).
Huntington disease (2 papers, 2012 to 2020). Huntington disease (HD) is a rare neurodegenerative disorder of the central nervous system characterized by unwanted choreatic movements, behavioral and psychiatric disturbances and dementia. "The nuclear transcription factor Y subunits NFYA and NFYC, which both contain high-scoring PrLDs affected by splicing, are sequestered in Htt aggregates in patients with Huntington’s disease." (PMID 31914925, 2020).
cerebellar degeneration (1 paper, 2014). Degeneration of the cerebellum. "Because complete elimination of HSPA5 in Purkinje cells leads to reduced cytosolic ubiquitination and accelerated cerebellar degeneration in a mouse model, HMGB1 could be a target of mutant TBP in SCA17, as well as NFYA." (PMID 25549101, 2014).
endometrial adenocarcinoma (1 paper, 2018). "NFYA-short, one of the alternatively spliced isoforms of NFYA, was found to have high transactivation ability in endometrial adenocarcinoma." (PMID 29467441, 2018).
pancreatic adenocarcinoma (1 paper, 2020). "Using the GSE15471 and TCGA-Pancreatic adenocarcinoma (PAAD) datasets, we analyzed the clinical importance of TOP2A-associated genes (HDAC1, HDAC2, HMGB1, HMGB2, NFYA, NFYB, NFYC, and SP1)." (PMID 32977589, 2020).
psoriasis (1 paper, 2022). An autoimmune condition characterized by red, well-delineated plaques with silvery scales that are usually on the extensor surfaces and scalp. "NFIC, NFYA, POU2F2, FOXA1 and SRF were discovered to be significant in psoriasis in our study after a gene-transcription factor regulatory network and several relevant transcription factors were evaluated." (PMID 36499614, 2022).
rheumatoid arthritis (1 paper, 2021). A chronic, systemic autoimmune disorder characterized by inflammation in the synovial membranes and articular surfaces. "A transcription factor analysis of age related CpGs revealed only a single motif: nuclear transcription factor Y Subunit Alpha (NFYA), which is involved in cancer, and rheumatoid arthritis." (PMID 34482522, 2021).
sarcoma (1 paper, 2023). A usually aggressive malignant neoplasm of the soft tissue or bone. "High expression levels of both ACVR2B and NFYA were in positive correlation with higher risk scores, suggesting that these two genes may act as risk factors for sarcoma development and clinical deterioration." (PMID 36769292, 2023). "Therefore, the results obtained in this study are theoretically and practically supported, suggesting that NFYA could also be a potential target for sarcoma therapy." (PMID 36769292, 2023). "However, no research has been performed on the potential of NFYA antagonists in sarcoma therapy." (PMID 36769292, 2023).